THBD (thrombomodulin)
Diseases named in the same sentence as THBD in open-access papers (continued):
Sharing a sentence is not in itself a finding about the gene and the disease.
COVID-19 (continued). "ICAM-1 and thrombomodulin levels trended higher in patients with positive as compared to negative D-dimers, regardless of COVID-19 positivity." (PMID 34491250, 2021). "This study assessed endothelial dysfunction and platelet activation biomarkers, including PAI, thrombomodulin, von Willebrand antigen (VWF: Ag), von Willebrand factor ristocetin cofactor (VWF: RCo), and P-selectin, to find a reliable biomarker to predict disease severity in COVID-19 patients." (PMID 40699808, 2025). "Notably, we found a similar association between respiratory dysfunction and the coagulation response, in that several markers, i.e., vWF, Thrombomodulin, Factor XII, and Factor VIII; correlated with respiratory SOFA and PaO2/FiO2 ratio solely in COVID-19 patients." (PMID 36829233, 2023). "In liver autopsy samples from patients who died because of COVID-19 complications, PC activation signaling receptors were significantly decreased compared with control as follows: 2.7-fold for S1PR1, 2.5-fold for F2R and 1.7-fold for THBD (p < 0.001), and less than 5% of cells expressed these genes." (PMID 36560757, 2022). "In a retrospective observational study, persistent endotheliopathy with increased levels of factor VIII, VWF, and thrombomodulin, compared with healthy subjects, was observed in convalescent COVID-19 patients, independent of ongoing acute phase response or NETosis." (PMID 34769508, 2021). "The results of our investigation suggest that thrombomodulin is significantly higher in ICU patients than in non-ICU patients and asymptomatic patients with COVID-19 patients, indicating endothelium damage." (PMID 40699808, 2025). "It has been shown that activation of vWF secretion and suppression of thrombomodulin and EPCR expression in the endothelium in COVID-19 do not require cell contact with viral particles." (PMID 39457048, 2024). "The authors also noted an increase in the receptor for thrombomodulin CD141 on nonclassical and intermediate monocytes in severe COVID-19 cases." (PMID 35632823, 2022). "Ang2 was significantly higher in ICU patients with COVID-19 requiring IMV compared to those who did not, as was thrombomodulin and vWF:Ag." (PMID 34446527, 2021).
endothelial dysfunction (69 papers, 2008 to 2026). In vascular diseases, endothelial dysfunction is a systemic pathological state of the endothelium (the inner lining of blood vessels) and can be broadly defined as an imbalance between vasodilating and vasoconstricting substances produced by (or acting on) the endothelium. "Further, increased soluble thrombomodulin levels reflect ongoing endothelial dysfunction and have previously been shown to be associated with relapse risk in iTTP." (PMID 39941363, 2025). "Occult hypoperfusion (associated with elevated plasma soluble thrombomodulin and syndecan-1, indicating shock-induced endothelial dysfunction) can occur in the setting of normal vital signs." (PMID 40576680, 2025). "A reduction in thrombomodulin, sE-selectin, sICAM-1 and proMMP-9, which are associated with endothelial dysfunction as bases of atherosclerosis, was observed." (PMID 36829862, 2023). "Hyperglycemia is associated with endothelial dysfunction and impaired thrombomodulin (TM)-dependent protein C activation." (PMID 36030260, 2022). "Plasma kynurenine levels were positively associated with thrombomodulin and von Willebrand factor (markers of endothelial dysfunction)." (PMID 35448889, 2022). "Hyperglycaemia is linked with endothelial dysfunction and diminished thrombomodulin (TM)-dependent protein C activation (aPC), and aPC has been shown to restrict maladaptive UPR-signaling." (PMID 35889743, 2022). "The increase of soluble thrombomodulin promotes protein C activation and is also seen in several pathologic conditions associated with endothelial dysfunction." (PMID 28267383, 2017). "A recently published general population-based study reports that endothelial dysfunction, as quantified by flow-mediated dilatation and circulating biomarkers (including thrombomodulin), was associated with a higher level of depressive symptoms." (PMID 26613755, 2016). "Additionally, endothelial dysfunction characterized by increased thrombomodulin and VEGFR‐1 expression is linked to a greater incidence of thromboembolic complications." (PMID 40944395, 2025). "The prothrombotic shift in infected lungs was revealed by increased expression of the coagulation cascade mediators TF, PLAT, PAI-1, THBD, and vWF associated with endothelial dysfunction as shown through the upregulated expression of ESAM, CD106, CD201, VEGF-A, and VEGFR-2." (PMID 38474396, 2024). "Endothelial dysfunction stimulates the release of thrombomodulin, which is associated with the progression of CKD stage, with parameters of kidney function including urea, creatinine, and cystatin C, and with hypertension, oxidative stress, and left ventricular hypertrophy." (PMID 39201390, 2024). "Additionally, endothelial dysfunction as reflected by increased thrombomodulin concentrations was associated with increased duration and severity of acute kidney injury following severe trauma." (PMID 36523784, 2022). "More recently, considerable evidence has shown that heart failure is associated with tissue ischemia and endothelial dysfunction, as assessed by impaired flow-mediated dilatation, as well as increases in specific plasma markers such as von Willebrand factor and soluble thrombomodulin." (PMID 18800166, 2008). "Whereas circulating levels of thrombomodulin in healthy individuals reflect the quantity of the receptor expressed on the endothelial cell surface, an increased proteolytic activity associated with endothelial dysfunction enhances its shedding from endothelial cells." (PMID 37760900, 2023). "The soluble pro-inflammatory adhesion molecules and thrombomodulin are the most sensitive biomarkers for identifying elevated endothelial dysfunction in women." (PMID 40332159, 2025). "Patients with HCM exhibit systemic evidence of endothelial dysfunction, as reflected by upregulated circulating levels of soluble thrombomodulin and tissue factor pathway inhibitor, including thrombomodulin and endothelial protein C." (PMID 40855573, 2025).
endothelial dysfunction (continued). "From a mechanistic point of view, hypercoagulability is associated with elevated vWF, endothelial dysfunction, elevated fibrinogen and factor VIII levels, and reduced thrombomodulin levels." (PMID 37507773, 2023). "Thrombomodulin, an integral membrane protein functioning as a cofactor in the anticoagulant pathways, has recently emerged as a marker of endothelial dysfunction." (PMID 35855391, 2022). "In a cross-sectional study of 55 T2DM patients, soluble thrombomodulin, another marker of endothelial dysfunction and potent activator of TAFI, was reported to be increased by 45% in patients with an HbA1c of 9.1%, when compared to control subjects." (PMID 34551784, 2021). "Endothelial dysfunction also impairs the activation of protein C, which depends on the endothelial protein C receptor and thrombomodulin, whose expression is reduced in damaged microvasculature, enhancing hypercoagulability status." (PMID 29694626, 2018). "Thrombomodulin concentration correlated significantly with other endothelial dysfunction and oxidative stress parameter concentrations: ADMA (R = 0.353; p = 0.010), BNP (R = 0.406; p = 0.001), and oxLDL (R = 0.340; p = 0.009)." (PMID 29682152, 2018). "This is, to our knowledge, the first study comparing thrombomodulin as endothelial dysfunction marker with oxidative stress markers in children with chronic kidney disease." (PMID 29682152, 2018). "In vivo study, bubble-induced EMPs were intravenously injected to the rats and soluble thrombomodulin, intercellular adhesion molecule 1, and vascullar adhesion molecule 1 were involved in evaluating endothelial dysfunction." (PMID 28114372, 2017). "This is consistent with other studies showing that serum THBD is increased in PE women compared to normal controls, and that THBD is a potential marker of endothelial dysfunction to predict PE." (PMID 27780539, 2016). "Elevated levels of thrombomodulin have also been reported in participants with chronic diseases such as T2DM caused by inflammation and endothelial dysfunction." (PMID 26613755, 2016). "Endothelial activation (soluble vascular cellular adhesion molecule-1) sVCAM-1, von Willebrand factor (vWF), thrombomodulin), endothelial dysfunction (determined by small artery elasticity (SAE)) and IMT were measured and related to AGE accumulation." (PMID 22168993, 2011). "We explored these polymorphisms in a case-control study and evaluated endothelial dysfunction by measuring several biomarkers including VWF, VCAM-1 and thrombomodulin, as well as the soluble form of CX3CL1." (PMID 19587779, 2009). "The increase of many markers of endothelial dysfunction, including thrombomodulin, von Willebrand factor (VWF) and VCAM-1, has been repeatedly reported in women with PE." (PMID 19587779, 2009). "However, and in contrast to thrombomodulin, little is known about the impact of endothelial dysfunction on the expression of EPCR on endothelial cells in the context of peripheral artery disease (PAD)." (PMID 37760900, 2023). "ELISA results showed NETs from TBI patients, especially those with coagulopathy, could significantly impair endothelial dysfunction by decreasing the expression of syndecan-1, thrombomodulin, and VWF." (PMID 36802340, 2023). "In severeP. falciparum malaria, adhesion molecule upregulation has been demonstrated and thrombomodulin levels (TM) have been reported to be high suggesting that any coagulation activation seen might be due to endothelial dysfunction." (PMID 39219856, 2023). "By promoting endothelial dysfunction, it can influence complex regulation of the hemostatic mechanism, triggered by decreased concentrations of tissue factor pathway inhibitor (TFPl) and thrombomodulin." (PMID 34177368, 2021).
endothelial dysfunction (continued). "The endothelial-mediated injury associated with air pollution and disease in young individuals was reported in one study of 125 children and adolescents aged 10–18 years, which only used thrombomodulin and tissue factor as surrogate markers for endothelial dysfunction." (PMID 33066786, 2020). "In children with chronic kidney disease, thrombomodulin seems to be a valuable marker of endothelial dysfunction, correlating strongly with CKD stage, kidney function parameters (urea, creatinine, and cystatin C), as well as oxidative stress, hypertension, and left ventricular hypertrophy." (PMID 29682152, 2018). "Indeed, other markers of endothelial dysfunction, such as von Willebrand's factor and soluble thrombomodulin, which correlate with left atrial volume in patients with lone permanent non-rheumatic AF, might have been of greater interest." (PMID 37539088, 2023). "SARS-CoV-2-Induced endothelial damage releases a variety of soluble markers of endothelial dysfunction, including von Willebrand factor (VWF), soluble E-selectin, P-selectin and thrombomodulin." (PMID 36522776, 2022). "Markers of endothelial dysfunction (ICAM1, VCAM, VEGFR3, thrombomodulin) and inflammatory response (CRP, MPO) were also noted to progressively increase with rising altitude in both groups, more prominently so in ICs and has been reported earlier by us." (PMID 37384264, 2022). "Our data showed that the mRNA expressions of vWF, ET, THBD, ICAM-1, and GMP140 were significantly increased, suggesting endothelial dysfunction." (PMID 34576058, 2021). "In contrast, endothelial dysfunction in the aorta was featured by impaired NO- and PGI2-dependent function and diminished thrombomodulin (CD141) expression." (PMID 29967661, 2018). "Subjects with chronic diseases related to inflammation and endothelial dysfunction, such as T2DM, have elevated levels of thrombomodulin." (PMID 26613755, 2016). "A recent report has suggested that endothelial dysfunction in FSGS, which involves increased levels of endothelial cell-derived circulating VCAM-1 and thrombomodulin levels, is largely related to disease activity." (PMID 26266776, 2015). "Endothelial dysfunction biomarkers including von Willebrand factor, VCAM-1 and thrombomodulin, as well as the soluble form of CX3CL1 were measured by enzyme-linked immunosorbent assays (ELISA)." (PMID 19587779, 2009). "Various markers of endothelial injury have been investigated in CAR-T cell recipients, including markers of complement activation, such as soluble C5b-9, endothelial dysfunction (angiopoietin-2, VCAM1, ICAM-1), inflammation, and thrombosis (von Willebrand antigen, ADAMTS13, thrombomodulin)." (PMID 40940973, 2025). "In our study, ELISA results validated that syndecan-1, soluble thrombomodulin, and VWF were positively correlated with NET markers, which indicated that NETs may participate in endothelial dysfunction in TBI." (PMID 36802340, 2023). "Given that thrombomodulin is released as a response to endothelial damage, we speculate that LSG leads to a significant improvement in preexisting endothelial dysfunction in morbidly obese subjects." (PMID 35855391, 2022). "The gene transcription levels of von Willebrand factor (vWF), endothelin (ET), thrombomodulin (THBD), granular membrane protein 140 (GMP140), and intercellular cell adhesion molecule-1 (ICAM-1) related to endothelial dysfunction were all significantly increased." (PMID 34576058, 2021). "Of note is that our results showed no significant changes in plasma thrombomodulin, a marker for endothelial dysfunction, at 5 min after administration of the lower- or higher-dose of cadmium." (PMID 31275174, 2019). "However, data concerning the change in thrombomodulin concentration after LSG and its association with endothelial dysfunction in subjects undergoing LSG has not been studied yet." (PMID 35855391, 2022).
endothelial dysfunction (continued). "In summary, the current evidence convincingly shows that endothelial dysfunction in T2DM, driven by disturbed signaling in the arterial wall along with overactive NOX, is related to hypofibrinolysis through increased expression of PAI-1, TF, thrombomodulin, and most probably TAFI." (PMID 34551784, 2021). "Previous studies have demonstrated increased circulating thrombomodulin as an indicator of endothelial dysfunction in patients with severe burns, but in this heterogeneous cohort, we observed only a minor, nonstatistically significant increase in plasma thrombomodulin on average." (PMID 34877937, 2021). "Interestingly, in the current study, PAI-1 was not a marker that was exacerbated by either eNOS deficiency or by aging in response to CLP (as opposed to many other markers of endothelial dysfunction that were exacerbated, including thrombomodulin)." (PMID 25223540, 2014). "No significant alterations in the serum markers of endothelial dysfunction/inflammation (spSelectin, seSelectin, PECAM-1, sICAM) or thrombosis (Thrombomodulin) were observed at 660 days post IR." (PMID 36982525, 2023).
Disseminated intravascular coagulation (49 papers, 2011 to 2026). Disseminated intravascular coagulation is characterized by the widespread activation of coagulation, which results in the intravascular formation of fibrin and ultimately thrombotic occlusion of small and midsize vessels. "In septic conditions, thrombomodulin expression can be compromised, leading to sepsis-associated disseminated intravascular coagulation (DIC)." (PMID 30275773, 2018). "• Thrombomodulin expression level of inflammatory monocytes shows a significant correlation with the known disseminated intravascular coagulation (DIC) markers and had diagnostic value for overt DIC." (PMID 21489300, 2011). "Indeed, recombinant sTM, by replacing the vasculitis-induced depletion of membrane-bound local thrombomodulin, has been implicated in protection or reversal of vascular injury, disseminated intravascular coagulation (DIC) and in animal models of ARDS." (PMID 34344416, 2021). "Administration of recombinant human soluble thrombomodulin (rTM) is often used in Japan to treat septic disseminated intravascular coagulation (DIC)." (PMID 35130927, 2022). "In cases of disseminated intravascular coagulation, the treatment of choice consists in administration of antifibrinolytics, all-trans-retinoic acid, and recombinant soluble human thrombomodulin." (PMID 35955419, 2022). "Recombinant thrombomodulin, a novel agent used for the treatment of patients with disseminated intravascular coagulation (DIC) in Japan, also displayed an effect on inhibiting NET formation in vitro." (PMID 34712384, 2021). "Recombinant human soluble thrombomodulin (rhsTM) comprises the extracellular domain of thrombomodulin; thus, it has been used for the treatment of disseminated intravascular coagulation (DIC)." (PMID 32015385, 2020). "Human recombinant thrombomodulin (rTM) is clinically applied as a therapeutic agent for disseminated intravascular coagulation." (PMID 32583160, 2020). "Soluble recombinant human thrombomodulin (rhTM), consisting of all the extracellular domains of thrombomodulin, has been used to treat patients with disseminated intravascular coagulation (DIC)." (PMID 32497259, 2020). "The patient was treated with supportive therapy, including steroid pulse therapy (intravenous methylprednisolone 1 g/d for 3 days) for HLH and intravenous recombinant thrombomodulin 19200 U/d for 7 days for disseminated intravascular coagulation." (PMID 31626125, 2019). "Recombinant human soluble thrombomodulin (rTM) has been established and introduced in the clinic as a standard treatment for disseminated intravascular coagulation (DIC)." (PMID 29511940, 2018). "Recombinant human soluble thrombomodulin (rTM) has been used for the treatment of disseminated intravascular coagulation in Japan, and an international phase III clinical trial for rTM is currently in progress." (PMID 30275773, 2018). "Recombinant human soluble thrombomodulin (ART-123) is a novel anticoagulant for patients with disseminated intravascular coagulation (DIC)." (PMID 28229162, 2017). "We report a case of disseminated intravascular coagulation after deceased donor liver transplantation (DDLT) treated with recombinant thrombomodulin (rTM)." (PMID 27495993, 2016). "Recently, it has been proven that polymyxin B hemoperfusion (PMX-HP) improves septic shock and recombinant human thrombomodulin (rhTM) controls disseminated intravascular coagulation (DIC)." (PMID 27468959, 2016). "Recombinant thrombomodulin (rTM) is widely used for septic disseminated intravascular coagulation (DIC) in Japan." (PMID 26002185, 2015). "Thrombomodulin alfa (TM-α, recombinant thrombomodulin) significantly improved disseminated intravascular coagulation (DIC) when compared with heparin therapy in a phase III study." (PMID 25520842, 2014).